MPO (myeloperoxidase)
Diseases named in the same sentence as MPO in open-access papers (continued):
Sharing a sentence is not in itself a finding about the gene and the disease.
infection (continued). "Mutations in human MPO and genetic ablation in mice have repeatedly been linked to enhanced pathogen infection." (PMID 33273015, 2021). "Since Shigella and Campylobacter are known pathogens that cause inflammatory diarrhea, a positive association was expected between the level of MPO and infection with any of these pathogens." (PMID 29415075, 2018). "A clear illustration of the role of MPO is also observed in MPO knockout mice, which are highly susceptible to infections by Klebsiella and Candida and show persistent inflammation." (PMID 29669993, 2018). "MPO deficiency led to elevated pulmonary IL-1β expression in response to WT C. albicans indicating that during infection, neutrophils upregulate IL-1β production in an alternative ROS-dependent manner." (PMID 28314592, 2017). "Different publications have reported that serious infections as sporadic cases developed in less than 5 % of the individuals with MPO deficiency." (PMID 26719776, 2015). "Severity of infection, bacterial recovery, myeloperoxidase (MPO) activity and percent loss of retinal function were determined." (PMID 23496928, 2013). "Monitoring MPO may aid in identifying individuals at bidirectional infection risk, suggesting novel insights into the inflammation–infection interplay." (PMID 40943779, 2025). "RCS-based threshold analysis identified a nonlinear inflection at 24.0 ng/mL of MPO, where each additional 1 ng/mL of MPO below this threshold was associated with a reduced infection risk (OR = 0.959, 95% CI: 0.947–0.971), whereas levels above increased the risk (OR = 1.004, 95% CI: 1.002–1.007)." (PMID 40943779, 2025). "However, their efficacy in NET-associated pathologies remains to be investigated and the potential risks of MPO inhibition, such as increased susceptibility to infection, should be considered." (PMID 39905519, 2025). "Nevertheless, the risk factors for infection in older adults with myeloperoxidase-antineutrophil cytoplasmic antibody-positive AAV (MPO-AAV) receiving guideline-concordant therapy remain unclear." (PMID 41408511, 2025). "To assess whether increased QcrC expression is associated with the pathogenic state of C. jejuni, we used neutrophil myeloperoxidase (MPO) level in the feces as a marker of intestinal inflammation in a murine model of infection." (PMID 39015740, 2024). "Moreover, there was a significant elevation of MPO level which is a marker for a neutrophil’s alteration due to infection with the highly pathogenic E. papillata." (PMID 39055709, 2024). "In addition, MAL-ED investigators found that myeloperoxidase was associated with pathogen infection, and more specifically, that Campylobacter and myeloperoxidase were positively associated across all eight study sites." (PMID 38585931, 2024). "Serum levels of SAA and MPO were increased in animals that received a protein-deficient diet before (4544 ± 644.3pg/ml and 784 ± 47.62μg/ml) and after infection (4792 ± 309.5 and 742.1 ± 55.11) when compared to the uninfected nourished mice (2526 ± 258.1pg/ml and 527.5 ± 70.86μg/ml)." (PMID 37150212, 2023). "Neutrophils from these mice exhibited normal respiratory burst, ROS production, and iodination, but the mice were unable to resist infection with S. aureus (a prominent cause of infection in CGD) or Candida albicans (which also causes severe infection in MPO‐deficient mice)." (PMID 36440666, 2023). "However, increased susceptibility to severe infection in patients with MPO deficiency is documented so far in bacterial infection." (PMID 36510129, 2022). "Consistent with the microbicidal effects of MPO-catalyzed reactive species, MPO deficient mice were more likely to be infected or die from infection employing various models, suggesting that the MPO-dependent oxidative system is important for host defense against some fungi and bacteria." (PMID 35211113, 2022).
infection (continued). "During infection, MPO is involved in the inflammatory response, but it can cause oxidative reactions and the formation of large amounts of oxides, which may cause damage to the tissues." (PMID 35967416, 2022). "In vitro, phagocytes deficient in MPO exhibit a severe defect in killing C. albicans and hyphal forms of Aspergillus fumigatus, and patients with hereditary MPO deficiency have an increased susceptibility to infections with these fungi." (PMID 32661559, 2021). "Moreover, significantly lower concentrations of myeloperoxidase (MPO), an index of neutrophils infiltration into the injured tissue, were detected in the brains of IL-1R deficient mice after infection with GAS or S. aureus." (PMID 33525468, 2021). "However, the importance of host ROS in controlling S. aureus infection real-life infections is clearly demonstrated with increased S. aureus pathogenicity in MPO (or NOX2) deficient mice, as well as the attenuation of S. aureus katA ahpC infection in vivo." (PMID 34529737, 2021). "Nevertheless, here we demonstrated that MPO is an important host defence enzyme in vivo, where its loss resulted in increased bacterial load in the liver highlighting HOCl as an important ROS in the control of infection." (PMID 34529737, 2021). "In addition, PTX3 deficiency was associated with a higher amount of MPO (P = 0.004 at 44h after infection) and a higher percentage of neutrophils in the lung (P = 0.04 at 44 hours after infection)." (PMID 34093560, 2021). "However, several studies have shown that the majority of MPO-insufficient humans are asymptomatic, although the risk of severe infections was higher." (PMID 33569056, 2020). "Repeated neutrophil damage during every dialysis session may be involved in increased susceptibility to infection, and MPO release enhances oxidative stress, resulting in a state of chronic microinflammation for dialysis patients." (PMID 33303892, 2020). "Importantly, however, compared with infection with P. gingivalis, inoculation with P. gingivalis plus pyocyanin was associated with the much higher myeloperoxidase activities and hence the greatest neutrophil influx into the lung." (PMID 25706529, 2015). "It has been suggested that chronic inflammatory process and serious infections may be more frequent in patients with total or subtotal MPO deficiency." (PMID 26719776, 2015). "A major limitation in the approach to develop inhibitors of MPO and NETosis is the fact that neutrophil function is crucial for bacterial clearance, and core neutrophil bactericidal activity can facilitate pathogen invasion and colonisation, thus increasing the risk of infection and inflammation." (PMID 34724042, 2022). "Additionally, NAG and MPO assay results showed accumulation of inflammatory cells in the lungs, which are important cells to control the fungal burden, preventing tissue architecture loss secondary to infection." (PMID 34359982, 2021). "For example, HOCl/OCl- is primarily produced in response to infection and/or inflammation by certain immune cells that express myeloperoxidase (MPO)." (PMID 41837562, 2026). "NETs, which contain antimicrobial compounds such as myeloperoxidase (MPO), represent a strategy to combat infection." (PMID 40696821, 2026). "Late infection featured further Th1 reduction, neutrophil accumulation, and NETs activation (H3cit, NE-DNA, MPO), along with reduced CXCL9 but elevated IL-6, IL-21, IL-27, CXCL10, and S100A8 in blood." (PMID 42112327, 2026). "Both cfDNA and MPO–DNA complex levels were significantly increased in neutrophil supernatants following ΔsodA infection compared with WT, whereas the complemented strain restored these levels close to those of WT." (PMID 41294351, 2026). "In older adults with MPO-AAV, TMP-SMX use was associated with a reduced risk of early severe infection." (PMID 41408511, 2025). "We performed MPO immunohistochemical staining on lung tissues from the three groups of mice 24 h after intranasal infection with K. pneumoniae." (PMID 40817809, 2025).
infection (continued). "Compared to the reference tertile (T2), participants in both the lowest (T1) and highest (T3) MPO tertiles exhibited elevated infection odds (T1: OR = 1.15, 95% CI: 1.05–1.25, p = 0.002; T3: OR = 1.18, 1.08–1.28, p < 0.001)." (PMID 40943779, 2025). "Along with the MPO results, these data suggest that intradermal infection by the Cn H99 strain induces a stronger inflammatory immune response than that by the Cd B3501 strain." (PMID 40067245, 2025). "Most existing research has primarily focused on changes in MPO levels in response to established infection." (PMID 40943779, 2025). "Myeloperoxidase (MPO) is released by neutrophils and is indicative of the number of these cells at a site of infection." (PMID 40067245, 2025). "Using RT-qPCR to quantify proinflammatory MPO, S100a8, as well as iNOS expression in neutrophils, we observed significant upregulation after 6 h of infection with fas2Δ/Δ compared to WT." (PMID 40138332, 2025). "Neutrophil extracellular traps (NETs), emerging as new biomarkers of infection and inflammation, are extracellular reticular structures composed of a DNA skeleton and a variety of granule proteins such as myeloperoxidase (MPO) and neutrophil elastase (NE)." (PMID 40256453, 2025). "Activated neutrophils release enzymes, such as reactive oxygen species, proteases and myeloperoxidase, which combat foreign organisms at the infection site." (PMID 40639060, 2025). "TxA2 is thought to activate neutrophils through receptor binding and by doing so promotes MPO production and the formation of NETs, which are essential antimicrobial functions to prevent infection." (PMID 39891428, 2025). "8–10 Patients with MPO deficiency exhibit a less dramatic phenotype than do patients with CGD, but frequently experience severe infections with Candida albicans, particularly in the presence of concomitant diabetes mellitus." (PMID 41393901, 2025). "We have previously shown that DKK1 signaling via PMN-LRP6 increased neutrophil MPO expression in the infection site of L. major infected mice." (PMID 40502169, 2025). "Biochemical indicators showed that IA pretreatment reduced the infection-induced abnormal rise in lung MPO levels." (PMID 40736248, 2025). "In conclusion, among the elderly patients with MPO-AAV, TMP-SMX use was associated with the occurrence of early severe infections after remission-induction therapy." (PMID 41408511, 2025). "After the Shigella infection, MPO concentrations declined throughout the following 6 months, and concentrations were lower by 6 months post-infection [MPO 6-month difference: -0.16 ln(nm/mL) (95% CI: -0.26, -0.04)]." (PMID 40440324, 2025). "Crucially, the core MPO–infection relationship remained robust across analyses adjusting metabolic diseases, demonstrating stability despite cohort selection." (PMID 40943779, 2025). "Compared to the number of F4/80+ cells, the number of MPO+ cells in the cKP infection group was significantly lower than that in the hvKP infection group at 24 hpi." (PMID 40742124, 2025). "MPO content in the lung tissue of mice in the Abx + AF group was significantly lower than that in the Abx group 24 h after infection with K. pneumoniae." (PMID 40817809, 2025). "NETosis is a form of cell death resulting in expulsion of a decondensed chromatin scaffold studded with antimicrobial products, such as myeloperoxidase (MPO), cathelicidin, and histones, that trap extracellular pathogens aiding in infection control." (PMID 39589812, 2025). "Specifically, MPO was significantly lower with Shigella among children with macrolide antibiotic use 15 days before or after infection at 5-months post-infection only." (PMID 40440324, 2025). "Previous research has demonstrated that neutrophils contribute to mucosal injury by producing reactive oxygen species with antimicrobial properties and releasing myeloperoxidase and elastase from their granules, which form fibrous networks to combat infection." (PMID 40356724, 2025).
infection (continued). "During infection, MPO, which is predominantly expressed by neutrophils, is often upregulated as part of the acute inflammatory response." (PMID 41465092, 2025). "Using RT-qPCR, flow cytometry, and ELISA, we found that the mRNA and protein levels of CXCR2, PSGL-1, and MPO in the neutrophils of the MRSA + Lanata group increased significantly at 6 h post-infection and were lower than those in the MRSA group after 12 h." (PMID 39877391, 2024). "Overall, these results reveal that B5 decreases the level of myeloperoxidase and promotes the production of lysozyme in the later infection phase." (PMID 39408834, 2024). "After treatment, the RRE attenuates the inflammatory response, since it suppresses the release of the infection-induced MPO level nearly to the normal status of the control group." (PMID 39055709, 2024). "During infection, activated neutrophils, via the Myeloperoxidase (MPO) system, produce hypochlorite (HOCl), which oxidizes free amino acids with the formation of Advanced glycation end products (AGEs)." (PMID 38732239, 2024). "By 7 d post-infection, fewer MPO + cells were detected in lung tissue and quantification revealed similar numbers across all groups (n.s.)." (PMID 38720343, 2024). "In murine models, it has been demonstrated that lower doses of MPO-ANCA induce glomerular leukocyte adhesion only after an infection-related stimulus, while higher antibody doses can induce it independently through alternative adhesion mechanisms." (PMID 38445024, 2024). "Altogether, the data suggest that in UM, processes such as NETosis (MPO and cfDNA) and active coagulation (D-dimers) are early events in infection that correspond to elevated anti–PF4/P IgG levels." (PMID 38652559, 2024). "While the controlled release of MPO at the site of infection is essential for its effective antimicrobial activities, uncontrolled degranulation can exacerbate inflammation and result in tissue damage, disregarding the presence of an inflammatory process." (PMID 38785813, 2024). "At tissue sites of infection or inflammation, MPO is released in large amounts from degranulating activated neutrophils." (PMID 39061857, 2024). "Data reveal a marked increase in the protein expression of NET-related markers such as MPO, NE, and citH3 at 4 dpi, indicating a strong activation of neutrophils and the formation of NETs early in the infection process." (PMID 39337543, 2024). "The presence of NETs in WT and THP KO urine samples at 24 h post-infection was visualized by immunofluorescence microscopy using antibodies for neutrophils (myeloperoxidase, MPO), NETosis (citrullinated histone H3, H3Cit), and THP." (PMID 38370726, 2024). "In the context of infection, MPO-catalysed oxidative reactions contribute to the innate immune defence and the inflammatory phase of wound healing." (PMID 39061857, 2024). "MPO is involved in the bactericidal activity of neutrophils and is released when neutrophils are activated to remove the source of infection." (PMID 38912048, 2024). "Neutrophils release various toxic molecules—such as reactive oxygen species, myeloperoxidase, glucosidase, proteases, and antimicrobial peptides—when activated by inflammation or infection." (PMID 39444808, 2024). "In contrast, by day 7 post-infection, urine MPO levels were close to baseline and comparable between groups." (PMID 39297649, 2024). "Mice administered C. jejuni cultured on blood agar showed little fecal MPO throughout the experimental period, whereas fecal MPO was significantly increased on days 2 and 3 after infection in mice given C. jejuni cultured in Bolton broth." (PMID 39015740, 2024). "Our model captures two key features of human infection: (i) a sustained and robust bacteriuria upon infection and (ii) the recruitment and activation of innate immune cells and detection of IL-8 and MPO biomarkers." (PMID 39297649, 2024).
infection (continued). "In parallel, both vaccines significantly reduced levels of inflammatory biomarkers IL-8 and myeloperoxidase in the urine at day 2 post-infection relative to placebo." (PMID 39297649, 2024). "MPO is secreted under certain conditions such as chronic inflammation, infection, and other conditions that involve the immune system." (PMID 39810847, 2024). "None of the major neutrophil effector molecules Elastase (ELANE), Proteinase 3 (PRTN3), Cathepsin G (CTSG) and Myeloperoxidase (MPO) changed significantly in response to infection." (PMID 38472281, 2024). "We found that, similar to that observed with expression of PSGL-1 and CXCR2, MPO expression in the neutrophils of Lanata-treated mice increased at 4 h and 6 h post-infection, reaching the peak at 6 h." (PMID 39877391, 2024). "NETs serve to ensnare and eliminate invading pathogens at infection sites, and are comprised of a complex matrix of DNA, histones, myeloperoxidase (MPO), neutrophil elastase (NE), and antimicrobial granules." (PMID 39087372, 2024). "Corroborating these results, we observed that release of neutrophil elastase and myeloperoxidase into the cell supernatants following infection was largely dependent on GSDMD." (PMID 38553499, 2024). "Our present study utilized quantitative assays to measure MPO and IL-8 levels in urine post-infection and thus provides an updated, precise, less subjective measure of local bladder inflammation." (PMID 39297649, 2024). "Results showed that the MPO-positive cells gradually increased after infection, significantly increased at 48 hours post-infection, and reached the top at 72 hours post-infection." (PMID 39435479, 2024). "Our results demonstrated that the GV-infected mice group was characterized by an elevated MPO activity at 7 days post-infection." (PMID 36807330, 2023). "A similar study showed a significant increase in serum myeloperoxidase at an early infection in P. sarana following an intra-peritoneal challenge with A. hydrophila." (PMID 37112789, 2023). "We labeled MPO with luminol, and the bioluminescence results showed significantly higher local MPO activity in TRPV1−/− mice than that in WT mice 1 day after infection." (PMID 38129779, 2023). "The ability of MPO-knockout (KO) to fight against pathogens has revealed the role of this component in the host’s defense against infection." (PMID 38037141, 2023). "Once neutrophils arrive at the infection site, they express metabolites such as lactoferrin (LF), myeloperoxidase (MPO), and nitric oxide (NO)." (PMID 37215733, 2023). "Mtb-infected lungs at 1 day post-infection exhibit undetectable MPO while high levels of MPO are evident inside inflammatory cell aggregates at 30 days post-infection in both WT and Duox1 KO mice." (PMID 36936954, 2023). "Myoglobin (p = 0.02), VCAM1 (p < 0.0001), and myeloperoxidase (MPO) (p < 0.0001) were all significantly upregulated in the plasma of the severe infection group compared to healthy controls." (PMID 37598150, 2023). "The main inflammatory cell recruitment was observed during the invasive phase of the infection (starting from 24 hr after infection), when the pulmonary MPO was dramatically increased." (PMID 37222419, 2023). "The development of histological damage after GV infection was accompanied by an increase of MPO activity." (PMID 36807330, 2023). "C. parvum-infected mice showed sustained stool oocyst shedding for six days post-infection and increased fecal MPO and inflammation scores." (PMID 37150212, 2023). "During infection, ɑSyn expression coincides with the infiltration of neutrophil leucocytes, as indicated by increased levels of myeloperoxidase (MPO) protein expression." (PMID 36991261, 2023). "The DNA backbone, together with the presence of histones, MPO and other granule proteins, can all contribute to pathogen killing in the extracellular environment and assist in clearing infection." (PMID 36830036, 2023).